IFNG (interferon gamma)
Diseases named in the same sentence as IFNG in open-access papers (continued):
Sharing a sentence is not in itself a finding about the gene and the disease.
Chlamydia infection (57 papers, 2008 to 2025). "We used intracellular cytokine staining and flow cytometry to determine the effects of IFNε deficiency on NK cell number, phenotype, activation, and IFNγ production during Chlamydia infection in the FRT following the gating strategy shown in Fig. EV1D–F." (PMID 38263527, 2024). "Chlamydiae infection is associated with changes in the vaginal microbiome that can impact IFNγ-mediated immune response." (PMID 36838426, 2023). "Our study identified TLR5, STAT2 and IFNγ as genes significantly associated with the ability of a koala to resolve a Chlamydia infection." (PMID 35510793, 2022). "Animal models and natural history studies of Chlamydia infection have revealed interferon gamma (IFN-γ)-producing CD4+ T cells as correlates of protection against re-infection." (PMID 40005489, 2025). "During a natural Chlamydia infection, the inflammatory cytokine IFNγ is produced by the innate immune response as well as CD4 +T cells and is thought to have a protective effect against infection." (PMID 39804088, 2025). "In this study, we show that IFNε is responsible for promoting the infiltration, activation, and IFNγ production of NK cells in the uterus during Chlamydia infection." (PMID 38263527, 2024). "Since NK cells can influence T cell polarity and T cells are another source of IFNγ during Chlamydia infection, we also assessed the effect of IFNε on IFNγ production by T cells during infection." (PMID 38263527, 2024). "Previous studies showed that NK cells are the predominant source of IFNγ early during Chlamydia infections, with NK cell depletion resulting in diminished IFNγ expression, a shift from Th1-dominant to Th2-dominant responses, and delayed clearance." (PMID 38263527, 2024). "Strong interferon (IFN)γ and adaptive Th1 responses promote the clearance of Chlamydia and limit the development of disease and the production of IFNγ during the early stages also plays an important role in controlling Chlamydia infections." (PMID 38263527, 2024). "A major player in clearing Chlamydia infections is the inflammatory cytokine interferon-γ (IFNγ), which is produced by immune cells that are recruited to the site of infection." (PMID 39194253, 2024). "Natural killer cells (NK cells) promptly migrate to the infected tissue during Chlamydia infection and serve as the primary early producers of IFNγ, which plays a pivotal role in shaping the adaptive immune response." (PMID 39065071, 2024). "We show that the constitutive expression of IFNε in the uterus plays a crucial role in promoting the accumulation, activation, and IFNγ production of NK cells in uterine tissue during Chlamydia infection." (PMID 38263527, 2024). "A large amount of evidence has demonstrated that naive CD4+ T cells differentiate and develop into IFNγ-secreting Th1 cells under the action of IL-12, which is the main adaptive cell type for defense and clearance of primary Chlamydia infection." (PMID 39065071, 2024). "Innate IFNγ plays a crucial role in limiting early C. muridarum dissemination, while Th1-derived IFNγ is essential for eradicating established Chlamydia infections." (PMID 39065071, 2024). "Although IFNγ production by CD4+ T cells in response to Chlamydia infection has been described, the role of distinct innate immune cell populations remains poorly defined." (PMID 34938670, 2021). "Among the target genes, we found the key antichlamydial gene ido1 which is known to be induced by Chlamydia infection and interferon, especially IFNG." (PMID 34819931, 2021). "A key factor in human intracellular defense against Chlamydia infection is the infection- and IFNG-induced host indoleamine 2,3-dioxygenase (IDO) activity." (PMID 34819931, 2021). "While they differ mechanistically, these findings coincide with our observations that the effect of IFNγ on bystander cells limits the spread of a primary Chlamydia infection in vitro." (PMID 29855501, 2018).
Chlamydia infection (continued). "One of the most important immune responses for the development of protective immunity against Chlamydia infection is characterized by antigen-specific interferon-gamma (IFN-γ) secretion by CD4+ T cells." (PMID 29404279, 2018). "As observed previously, Chlamydia infection attenuated nuclear accumulation of pSTAT1 when IFNγ was added at the time of infection." (PMID 29855501, 2018). "Such activity could be particularly significant during Chlamydia infection, where IFNγ plays a pivotal role in determining the outcome of infection." (PMID 40405396, 2025). "Moreover, CPE2_0552 inhibited the secretion of interferon gamma (IFNγ), a key cytokine that influences the outcome of Chlamydia infections." (PMID 40405396, 2025). "In short, expression of several ISGs are induced by IFNγ, and whether they are all relevant to Chlamydia infection needs to be addressed, with multiple ISGs acting in combination to control chlamydial growth." (PMID 39194253, 2024). "Previous studies showed that NK cells are important in immune protection against Chlamydia infections through the production of IFNγ, subsequent promotion of protective Th1 adaptive immunity via modulation of DC function, and killing of Chlamydia-infected cells." (PMID 38263527, 2024). "IFNγ is required for activation of the antibody‐mediated response to Chlamydia infection." (PMID 35510793, 2022). "Western blot was used to determine whether Chlamydia infection and/or IFNG treatment induced IDO1 protein expression." (PMID 34819931, 2021). "IFNγ is critical for protection against Chlamydia infection." (PMID 34938670, 2021). "The first and most important immune response to Chlamydia infection is a local one, whereby immune cells such as leukocytes are recruited to the site of infections, and subsequently secrete pro-inflammatory cytokines and chemokines such as interferon gamma." (PMID 25386180, 2014). "The primary defense against Chlamydia infection in the mouse involves the IFNγ-inducible family of IRG proteins; however, the precise mechanisms mediating the pathogen's elimination are unknown." (PMID 19242543, 2009). "One of the major immune mechanisms for controlling Chlamydia infection occurs through depletion of cellular tryptophan (TRP) by indoleamine-2,3-dioxygenase (IDO) – a TH1 process that is mediated by interferon gamma (IFN-g)." (PMID 19727394, 2009). "The present study shows that 7 days after genital Chlamydia infection, CCL5, CCR5, and IFNγ mRNA levels were elevated in inductive sites, while CCR5 mRNA expression was higher in the fallopian tubes than in the uterus and cervix." (PMID 18700040, 2008). "Irgm1 and Irgm3 have been shown to be critical regulatory factors for IFNγ-mediated defense against C. trachomatis, but the collective roles of Irgm proteins in host defense and the regulation of inflammation in Chlamydia infection have not been studied." (PMID 38501887, 2024). "Since activated T-bet+ RORγt+ ILC3s produce IFNγ and adoptive transfer of RORγt+ ILC3s protected mice from intestinal colonization with Chlamydia mutant, it was proposed that ILC plasticity can occur in response to Chlamydia infection." (PMID 36838426, 2023). "The tryptophan-degrading activity of IDO1 was not induced significantly by Chlamydia infection alone, but the addition of IFNG greatly increased its activity." (PMID 34819931, 2021). "However, during Chlamydia infection in vitro, addition of IFNγ does not fully induce nuclear localization of its transcription factor STAT1 and expression of its target gene, IDO1." (PMID 39194253, 2024).
lung disease (57 papers, 2004 to 2026). "As expected from previous analyses there was a clear association of IFNγ TThi with pulmonary disease while IFNγ AAlo was clearly associated with increased risk of PAD and DTB." (PMID 19274101, 2009). "A previous study demonstrated that IFNγ was upregulated in physiologically aged lungs, implying that IFNγ signaling might be linked to aging-related lung diseases." (PMID 37199578, 2023). "Adaptive mechanisms increasingly contribute to complications: both macrophage activation syndrome and lung disease demonstrate IFNγ-dominant pathology with T cell hyperactivation." (PMID 41627555, 2026). "The use of emapalumab (anti-interferon gamma antibody) for the active control of MAS in refractory cases of sJIA and associated lung disease has not been reported." (PMID 36891226, 2023). "Secondly, to investigate whether the pulmonary profile of CD4 + Il13+, CD4 + Ifnγ + and CD4 + Il17+ cell numbers at any of the assay times was, collectively, predictive of later lung disease we performed multiple linear regression analyses on these data." (PMID 25889053, 2015). "Moreover, studying twin pairs longitudinally will enable a better understanding of the possible molecular linkage between lung disease and methylation of CpG sites in FOXP3 and IFNγ in Treg and Teff, respectively." (PMID 23226205, 2012). "Mediating pathways shared by all three pulmonary disorders favor innate immune and inflammation-related processes, including toll-like receptor (TLR) signaling, PDGF- and angiotensin-regulated airway remodeling, the JAK-STAT signaling pathway, and interferon gamma." (PMID 30971743, 2019). "Furthermore, absence of IFNγ or of IFNγ signaling in the recipients' pulmonary parenchymal cells promoted expansion of IL-17A-producing cells, thus increasing the severity of lung disease." (PMID 23843069, 2013).
cyst (56 papers, 2010 to 2025). A sac-like closed membranous structure that may be empty or contain fluid or amorphous material. "Control of parasite replication requires the continuous presence of IFNγ-producing T cells to keep T. gondii in its slowly replicating cyst form." (PMID 33633185, 2021). "We observed that both cyst load and behavior were correlated with the expression levels of interferon-gamma (IFN-γ), interleukin-12b (IL-12b), and tumor necrosis factor (TNF)." (PMID 31940479, 2020). "IFNγ produced by CD8 T cells is crucial for the maintenance of the quiescent cyst form of Toxoplasma." (PMID 29922298, 2018). "Maintenance of IFNγ is necessary to prevent cyst reactivation." (PMID 22912696, 2012). "Limitation of parasite replication and cyst formation relies on the development of a type 1 T helper (Th1) response involving secretion of IL-12 by dendritic cells and interferon-gamma (IFN-γ) and tumor necrosis factor (TNF) by T cells and natural killer (NK) cells." (PMID 21698150, 2011). "Subsequently, a research published on the nature journal demonstrated that the IFNγ secretion of CD8+ T cells activated by PD-L1 blockage promoted ferroptosis of CD45- ID8 cells, and combination of cyst(e)inase and PD-L1 blockage significantly increased the anti-cancer efficacy." (PMID 37182170, 2023). "These functions occur non-sequentially driven by immune responses but are genetically pre-programmed hence cyst formation even in the absence of IFNγ." (PMID 37675999, 2023). "The cytokine IFNγ is critical for protection against toxoplasmic encephalitis (TE) in part by limiting parasite replication in astrocytes; indeed, in the absence of IFNγ signaling, cyst formation is observed in astrocytes." (PMID 37675999, 2023). "Further, cytokines such as interferon-gamma (IFN-γ), interleukin-6 (IL-6), IL-12b, and tumor necrosis factor (TNF) are considered signatures of T. gondii infection in the CNS of mice and have been positively correlated with cyst load and behavior." (PMID 35857765, 2022).
Hyperglycemia (56 papers, 2010 to 2026). An increased concentration of glucose in the blood. "We show that cytokines, such as IFNγ and IL-4, define the direction of macrophage response, whereas hyperglycemia interferes by enhancing or annulating this cytokine effect." (PMID 35163309, 2022). "CD163 gene expression was decreased 5.53 times in M(IFNγ) with a further decrease of 1.99 times in hyperglycemia." (PMID 35163309, 2022). "Apart from IFNγ- and IL-4-mediated regulation of CD163, hyperglycemia elicited an additional suppression of CD163 mRNA in M(IFNγ) compared to normoglycemia." (PMID 35163309, 2022). "Overall, the strongest enhancing effect of hyperglycemia was detected for IL-1β release 24 h after M(IFNγ) was stimulated with 1 μg/mL Hb-Hp1-1 complexes (6.75 times)." (PMID 35163309, 2022). "Expression and/or activity of eNOS substantially decreases in response to classic atherogenic culprits such as chronic inflammation (TNF, interleukin 1, and IFNγ), oxidative stress, hypoxia, hyperglycemia, and dyslipidemias." (PMID 34026871, 2021). "In the diabetic mice with enhanced IFNγ signaling, the protective effects of microglia against brain microbleeds are impaired under hyperglycemia while inhibition of IFNγ restores the reparative function of microglia to vessel damage." (PMID 32878297, 2020). "We focussed on S100A9 and S100A12 as we found the expression of these genes to be increased by hyperglycemia during monocyte/macrophage differentiation under IFNγ stimulation." (PMID 32582175, 2020). "It is intriguing to point out that paraoxon pretreatment in IFNγ−/− mice did appear to protect against onset of hyperglycemia during the first 10 days following STZ administration." (PMID 27790217, 2016). "Hyperglycemia and inflammation create a feedback loop in which high blood glucose levels promote the release of pro-inflammatory cytokines and other inflammatory mediators like the interferon-gamma." (PMID 39896818, 2024). "Suppression of CD163 expression in M(IFNγ) in hyperglycemia raised the question of whether high-glucose conditions additionally have a direct impact on the scavenging function of CD163." (PMID 35163309, 2022). "However, hyperglycemia induced an inflammatory response of M(IFNγ) to Hb-Hp1-1 and Hb-Hp2-2 uptake with different dynamics." (PMID 35163309, 2022). "We showed that hyperglycemia enhanced the proinflammatory response of M(IFNγ) to Hb-Hp complex uptake by stimulating the production of TNFα, IL-1β, IL-6, IL-8, and IL-1RA, supporting the observation that hyperglycemia itself can induce the secretion of proinflammatory cytokines." (PMID 35163309, 2022). "Hyperglycemia suppressed CD163 surface expression in M(IFNγ) (1.43 times)." (PMID 35163309, 2022). "Interestingly, cellular immunity is inhibited in diabetic patients as hyperglycemia has been shown to inhibit maturation of dendritic cells and modify function of cytokines, such as IFNγ." (PMID 26904326, 2016). "Consistent with this conclusion, inhibition of AChE failed to prevent STZ-induced hyperglycemia in IFNγ-deficient mice." (PMID 27790217, 2016). "However, we identified that hyperglycemia enhances the release of inflammatory cytokines in response to scavenging of Hb-Hp complexes via CD163 in M(IFNγ), converting the silent Hb-Hp complex clearing process needed to prevent vascular damage into an inflammatory process." (PMID 35163309, 2022). "Although the extreme stimulation as achieved by ex vivo LPS/IFNγ-stimulation might not represent the in vivo situation, it uncovers altered susceptibility to immune-modulation with hyperglycemia." (PMID 30333571, 2018). "Interestingly, inhibition of AChE fails to modulate streptozotozin (STZ)-induced hyperglycemia in IFNγ-deficient (IFNγ−/−) mice, demonstrating the crucial role played by IFNγ in ACh-mediated inhibition of the autoimmune response against islet β cells." (PMID 27790217, 2016).
Hyperglycemia (continued). "The biological function of PTPN2 is believed to vary in response to proinflammatory stimuli such as interferon-gamma (IFN-γ), tumor necrosis factor (TNF-α), hyperosmotic stress, or hyperglycemia." (PMID 27995146, 2016). "Gysemans and colleagues found that loss of signal transducer and activator of transcript-1 (STAT-1), a transcription factor activated by both IFNγ and IFNα, prevents β-cell death in response to IFNγ and IL-1β in vitro, and protected from STZ-induced hyperglycemia in vivo." (PMID 34822454, 2021). "For the analysis of hyperglycemic memory in M1 macrophages, after 6 days, when the monocytes had differentiated into macrophages, the medium was changed from NG to NG, from HG to HG and from HG back to NG (transient hyperglycemia) while MCSF and IFNγ was maintained." (PMID 32582175, 2020). "When activated by hyperglycemia, retinal hypoxia, ischemia and ER stress, these cells are classified as M1 macrophages and release pro-inflammatory mediators such as IL-6 and IL-12, TNF-α and interferon gamma (IFN-γ), known inducers of inflammation, apoptosis and neurotoxicity." (PMID 37298672, 2023). "Importantly, pretreatment with paraoxon protected against STZ-triggered hyperglycemia in WT but not in IFNγ−/− mice." (PMID 27790217, 2016). "Chronic hyperglycemia modulates immune responses and triggers inflammation through the activation of Toll-like receptors (TLRs), leading to an increase in the proinflammatory cytokines, IL1, IL6, TNFα and interferon γ(IFNγ), and a decrease in the levels of interleukin 10 (IL10)." (PMID 24260283, 2013). "The highest effect of hyperglycemia was gene expression of S100A9 and S100A12, in particular in pro-inflammatory M1 macrophages which are maturated with MCSF and simultaneously stimulated with IFNγ, and for S100A8 in M0 macrophages, maturated without additional stimulation." (PMID 32582175, 2020).